LOXL4 (lysyl oxidase like 4)
Diseases named in the same sentence as LOXL4 in open-access papers (continued):
Sharing a sentence is not in itself a finding about the gene and the disease.
carpal tunnel syndrome (1 paper, 2026). Entrapment of the median nerve in the wrist that is characterized by numbness, tingling and painful movement. "These included associations with genes involved in neurotransmitter signaling (HTR3A), immune function (HLA-DQB1, BCL11A), extracellular matrix remodeling (COL11A1, ADAMTS17, LOXL4), axon guidance and neural development (DCC, ETV1, NEGR1), and carpal tunnel syndrome (DIRC3)." (PMID 41518141, 2026).
colorectal adenocarcinoma (1 paper, 2014). The most common type of colorectal carcinoma. "On the other hand, the tumor suppressor role of LOXL4 was also reported in colorectal adenocarcinomas." (PMID 25311867, 2014).
endometrioid ovarian carcinoma (1 paper, 2020). "When considering endometrioid ovarian carcinoma patients, the mRNA expression levels of LOX, LOXL1, LOXL2, LOXL3, and LOXL4 demonstrated no relation with OS or PFS." (PMID 33058284, 2020).
gastric tumor (1 paper, 2020). "LOXL4 can also increase GC cells adhesion with collagen I and fibronectin which is associated with gastric tumor cell migration and invasion." (PMID 32467737, 2020). "Moreover, LOXL4 induces gastric tumor cell proliferation and migration through FAK/SRC pathway and ERK phosphorylation." (PMID 32467737, 2020).
glioblastoma (1 paper, 2025). The most malignant astrocytic tumor (WHO grade IV). "To investigate the impact of the LOX family on glioblastoma, we analyzed the expression of LOX family members (LOX, LOXL1, LOXL2, LOXL3, and LOXL4) in normal human astrocytes (Heb) and glioblastoma cell lines (T98G and LN-229)." (PMID 40270974, 2025).
keratoconus (1 paper, 2019). A degenerative, structural disorder of the eye, characterized by a cone-shaped protrusion of the cornea. "In keratoconus, a disease characterized by irregular astigmatism resulting in significant visual impairment, LOXL3 expression is downregulated, as well as LOXL2 and LOXL4 expression, suggesting that LOX members may be involved in keratoconus pathogenesis." (PMID 31340433, 2019).
Keratocystic odontogenic tumor (1 paper, 2023). An intraosseous odontogenic neoplasm that usually arises from the mandible. "In keratocystic odontogenic tumors, LOXL4 gene was positively correlated with stromal microvessel density (r = 0.882) suggesting an involvement in enhancement of angiogenesis." (PMID 37296997, 2023).
larynx cancer (1 paper, 2022). A primary or metastatic malignant neoplasm involving the larynx. "The possible role of lysyl oxidase-like 4 as a tumor marker in advanced stage larynx cancer was investigated." (PMID 33757755, 2022). "Lysyl oxidase-like 4 expression emerges with advancing stages, is lost with worsening differentiation, and may have tumor suppressive properties in larynx cancer." (PMID 33757755, 2022).
lung adenocarcinoma (1 paper, 2021). A carcinoma that arises from the lung and is characterized by the presence of malignant glandular epithelial cells. "MiR-210 exerts its effects in lung adenocarcinoma cells by targeting Lysyl oxidase-like 4 (LOXL4)." (PMID 34199293, 2021).
mesothelioma (1 paper, 2020). A usually malignant and aggressive neoplasm of the mesothelium which is often associated with exposure to asbestos. "However, four (LOX, LOXL1, LOXL2, LOXL4) and three (LOX, LOXL1, LOXL4) members were present in the mesothelioma (MESO; 87 patients, 239 genes) and ovarian serous cystadenocarcinoma (OV; 427 patients, 209 genes) datasets." (PMID 33383846, 2020).
nasal polyps (1 paper, 2023). "We found that LOXL4 was upregulated in the nasal polyps of ECRSwNP patients." (PMID 37867480, 2023).
retinal degeneration (1 paper, 2025). Degeneration of the retina. "As expected, these include clock genes such as Cry1 and Nfil3 (up) and Per3 and Nr1d2 (down) but also a few other genes, notably linked to retinal degeneration such as Myo7A61 that was substantially downregulated, or Loxl4 and Ppard that were highly upregulated." (PMID 40171795, 2025).
sarcoidosis (1 paper, 2022). Sarcoidosis is a multisystemic disorder of unknown cause characterized by the formation of immune granulomas in involved organs. "In our study, LOXL1 and LOXL4 showed increased expression in the IPF group, as well as LOXL2 and LOXL4 in the sarcoidosis group." (PMID 35203313, 2022).
serous ovarian carcinoma (1 paper, 2020). "The results indicated that the overexpression of LOX, LOXL1, LOXL2, LOXL3, and LOXL4 mRNA in serous ovarian carcinoma patients was related to unfavorable OS and PFS." (PMID 33058284, 2020).
skin tumor (1 paper, 2022). "The high levels of LOX, LOXL2, and LOXL4 transcripts in α11-deficient CAFs are congruent with the observed formation of extensive, linear collagen bundles and a shift toward stiffer skin tumor tissue in this mouse strain." (PMID 36003785, 2022). "Also, LOXL2 and LOXL4 mRNA levels were markedly upregulated in α11-deficient skin tumors, on average by 300-fold and 50-fold relative to the controls, respectively." (PMID 36003785, 2022).
Stroke (1 paper, 2018). Sudden impairment of blood flow to a part of the brain due to occlusion or rupture of an artery to the brain. "We next assessed if the four genes (CCDC71L, PRKAR2B, ADAMTS9, LOXL4) identified through colocalization of cIMT/carotid plaque with tissue-specific eQTLs also showed evidence for colocalization with CHD and stroke traits." (PMID 30510157, 2018).
tumor (58 papers, 2014 to 2025). "Previous studies have suggested that increased levels of LOXL4 are linked to increased tumour proliferation or migration in various cancers, such as liver cancer, head and neck squamous cell carcinoma, oesophageal cancer, gastric cancer, and colorectal cancer." (PMID 39247609, 2024). "LOXL4 is known to be upregulated in HCC tumor tissues and such upregulation is associated with a poor prognosis for HCC patients." (PMID 37508544, 2023). "Elevated LOXL4 was associated with tumor differentiation, vascular invasion, and tumor-node-metastasis (TNM) stage." (PMID 30704479, 2019). "Consistent with previous studies, we found that LOXL4 significantly promoted cell adhesion, migration, and invasion in vitro and tumor metastasis in vivo via gain- and loss-of-function studies and provide strong evidence that LOXL4 is a key determinant of HCC metastasis." (PMID 30704479, 2019). "However, in bladder and breast cancer, LOXL4 might function as a tumor suppressor because its loss promotes cancer cell proliferation and metastasis." (PMID 30728460, 2019). "RT-qPCR and WB techniques were used to detect the expression of LOX, LOXL1, LOXL2, LOXL3, and LOXL4 in tumor tissues." (PMID 40270974, 2025). "Zeste homology 2 (EZH2), the catalytic subunit of PRC2 provokes the release of LOXL4 in tumor cells to modulate the activation of macrophage into TAMs via miR-29b/miR-30d-LOXL4 axis in TNBC." (PMID 38715072, 2024). "Injection of LOXL4 promotes macrophage infiltration, accelerates tumor growth, and facilitates immune evasion." (PMID 37626849, 2023). "LOXL4 has even been shown to play an important role in hepatocarcinogenesis by creating a microenvironment that is immunosuppressed during tumor development." (PMID 37508544, 2023). "Studies have shown that LOXL4 is extensively involved in tumor proliferation, metastasis, angiogenesis, and immunity." (PMID 36293126, 2022). "Increasing tumor size was expected to be another predictor for LOXL4 expression, as an enlarging solid tumor invariably becomes more hypoxic." (PMID 33757755, 2022). "In another study, splice forms of LOXL4 were found to promote tumor progression in xenograft mouse models." (PMID 35682926, 2022). "This study aims to characterize the relationship between tissue LOXL4 expression and tumor size, nodal metastases, chemoradiotherapy response, survival in locally advanced LSCC." (PMID 33757755, 2022). "This LOXL4-based tumor vaccine is expected to be adapted for patients with tumor-specific upregulation of LOXL4." (PMID 36293126, 2022). "Lysyl oxidase-like 4 expression was correlated with advanced tumor stage (p = 0.041) and better differentiation (p = 0.025) but was independent of tumor diameter (p = 0.456)." (PMID 33757755, 2022). "Next, a multivariate analysis was undertaken to ascertain that LOXL4 positivity was an independent factor for improved OS, particularly to avoid confounding with the effect of better tumor differentiation in LOXL4 positive patients." (PMID 33757755, 2022). "In human HCC tissue, the upregulation of LOXL4 expression is correlated with vascular invasion, tumor differentiation, TNM stage, a poor prognosis, and high PD-L1 expression level." (PMID 36293126, 2022). "LOXL4 is a hypoxia-activated enzyme that is highly specific for head and neck SCCs and is more strongly expressed by tumor cells in higher stages." (PMID 33757755, 2022). "The potential role of LOXL4 as a tumor suppressor at the cellular level also warrants further research to clarify the sophisticated function this novel marker has in tumor progression." (PMID 33757755, 2022).
tumor (continued). "Injection of LOXL4 promotes the infiltration of macrophages into the liver, and accelerates tumor growth." (PMID 35682926, 2022). "We analyzed clinical samples to detect the expression levels of LOXL1 and LOXL4 in both tumor and matched adjacent tissues." (PMID 32424143, 2020). "More tumor nodules and increased Ki67 staining were found in the lungs of the control group compared with the -shLOXL4 group, indicating that LOXL4 promoted growth and lung metastasis of MDA-MB-231 cells." (PMID 32754259, 2020). "BAPN treatment resulted in a significantly reduced tumor volume and tumor weight compared to saline treatment, implying the involvement of LOXL4 enzymatic activity in tumorigenesis." (PMID 32754259, 2020). "Recent studies have described the involvement of LOXL4 in cancer progression, with reports of both oncogenic and tumor-suppressive functions." (PMID 32754259, 2020). "LOXL4 serves as a tumor suppressor in human bladder cancer and lung cancer 28, 29, whereas it promotes proliferation and/or metastasis of gastric cancer, head and neck squamous cell carcinoma, and hepatocellular carcinoma 30-32." (PMID 32754259, 2020). "To illustrate, miR-135a-5p presents a tumor-promoting role as evidenced by in vitro and in vivo studies directly targeting LOXL4." (PMID 33371259, 2020). "Taken together, our data demonstrate a novel function of LOXL4 in tumor metastasis mediated by exosomes through regulation of the FAK/Src pathway and angiogenesis in HCC." (PMID 30704479, 2019). "LOXL4 is highly expressed in head and neck squamous cell carcinoma, where its expression levels correlate with lymph node metastases and higher tumor stages." (PMID 31130685, 2019). "The expression level of lysyl oxidase-like 4 (LOXL4) is related to the tumor staging of HCC patients and plays an important regulatory role in tumor progression and metastasis." (PMID 31815633, 2019). "Univariate and multivariate Cox regression analyses further confirmed LOXL4 expression as an independent predictor of the survival of patients with HCC in addition to tumor size and TNM stage." (PMID 30704479, 2019). "LOX and LOXL4 participate in tumor microenvironment remodeling and the formation of pre-metastatic niches." (PMID 29728125, 2018). "In our orthotopic primary tumor and lung metastasis models, we showed that LOXL4 knockdown increased primary tumor growth and metastasis in MDA-MB-231 cells." (PMID 28060764, 2017). "In contrast, LOXL4 promotes aggressive tumor progression and metastasis in colorectal and oral cancers." (PMID 28060764, 2017). "In the mouse xenograft model, LOXL4 knockdown increased primary tumor growth and lung colonization as well as collagen I and IV, lysine hydroxylase 1 and 2, and prolyl 4-hydroxylase subunit alpha 1 and 2 levels." (PMID 28060764, 2017). "Here, we injected mice with LOXL4-knockdown MDA-MB-231 cells, which are aggressive TNBC cells, to investigate the roles of LOXL4 in primary tumor growth and metastasis in a xenograft model." (PMID 28060764, 2017). "GSK-LSD1 inhibited tonsillar SCC patient-derived tumor xenografts and inhibited CCN2/CTGF, MMP13, LOXL4 and vimentin expression whereas the expression of the tumor suppressor E-cadherin increased." (PMID 29088714, 2017). "As expected, in vivo BLI signals were stronger in LOXL4-knockdown tumor sites (6.13×107 p/s/cm2/sr) than in control tumor sites (468.54×107 p/s/cm2/sr) (P = 0.035)." (PMID 28060764, 2017). "To date, knowledge about the precise molecular function of LOXL4 in tumors is very limited, even though links to tumor progression are established." (PMID 26265048, 2015).
tumor (continued). "Aberrant LOX, LOXL2, and LOXL4 expression are implicated in dysregulating the ECM and inducing a malignant phenotype and promoting tumor progression in EOC." (PMID 26579497, 2015). "Intriguingly, LOXL4 exhibited a protective effect on half of the tumours in terms of the PFI." (PMID 40179101, 2025). "Furthermore, HCC-derived exosomes transferred LOXL4 to HUVECs by a paracrine mechanism to enhance tumor angiogenesis." (PMID 41567219, 2025). "Earlier studies found that exposure of macrophages to LOXL4 induced an immunosuppressive phenotype in tumours and activated the expression of programmed death ligand 1 (PD-L1), which further suppressed CD8+ T-cell function and contributed to the formation of an immunosuppressive microenvironment." (PMID 39286023, 2024). "Consequently, the role of LOXL4 in promoting or inhibiting human malignant tumours appears to be contingent on the specific tumour cell environment and the stage of tumour advancement." (PMID 39247609, 2024). "The enhancing effect of LOXL4 on tumour growth and invasion could be attributed to the oxidative cross-linking of annexin A2, which in turn prevents the internalisation of integrin-β1." (PMID 37565736, 2023). "Our research has shown that LOXL4 may also have certain tumor suppressive properties, as patients with high LOXL4 expressing tumors have longer overall survival." (PMID 33757755, 2022). "The association between tumor differentiation and LOXL4 expression has not been debated thus far in the English literature." (PMID 33757755, 2022). "Moreover, overexpression of miR-328-5p, miR-210, and miR-135a-5p can promote the proliferation and migration of tumor cells by downregulating the expression of LOXL4 in NSCLC cells." (PMID 36293126, 2022). "LOXL4 acts to promote macrophage infiltration into the liver to support tumor growth." (PMID 33371259, 2020). "These cell lines were used to evaluate the effects of LOXL4 on tumor growth in vitro and in vivo." (PMID 32754259, 2020). "Next, to further explore the effect of LOXL4 on tumor metastasis in vivo, SK-Hep1 overexpressing LOXL4 (LOXL4/SK-Hep1) and control cells (vector/SK-Hep1) were orthotopically inoculated into the left hepatic lobe of mice or injected intravenously into nude mice." (PMID 30704479, 2019). "We speculate that LOXL4 executes its progressive or repressive roles in different tumors depending on tumor cell context and tumor stages." (PMID 30728460, 2019). "So, we then examined whether LOXL4 expression was induced by these two important parameters in the tumor microenvironment of HCC." (PMID 30704479, 2019). "We speculated that LOXL4 may be internalized though some carriers to function intracellularly, or tumor metastasis-related factors induced by LOXL4 secreted into the CM may promote cell migration." (PMID 30704479, 2019). "In an orthotopic xenograft model (n = 4 and 5 for the control and LOXL4-knockdown groups, respectively), LOXL4 knockdown increased tumor volumes in the 5th and 6th weeks after cancer cell injection compared to the control (P = 0.008 and P = 0.040, 5th and 6th weeks, respectively)." (PMID 28060764, 2017).